MIR1184-2 (microRNA 1184-2)
Synonyms: hsa-mir-1184-2
Gene: MicroRNA gene on chromosome X (155,383,100 to 155,383,198, reverse strand). Ensembl gene ENSG00000221190.
Homologues: Orthologues: chimpanzee ptr-mir-1184-1 (100% identical). Paralogues in human: MIR1184-1 (100% identical), MIR1184-3 (100% identical).